MMP2 (matrix metallopeptidase 2)
Diseases named in the same sentence as MMP2 in open-access papers (continued):
Sharing a sentence is not in itself a finding about the gene and the disease.
tumor (continued). "Bacillus anthracis (anthrax) toxin has been reengineered to target tumor cells that express urokinase plasminogen activator (uPA) and metalloproteinases (MMP-2), and has shown antineoplastic effects both, in vitro and in vivo." (PMID 32121654, 2020). "Tumor tissue was analyzed by immunohistochemistry for expression of uPA, uPA receptor, MMP-2, MT1-MMP and TIMP-2." (PMID 32121654, 2020). "Inhibition of CD155 has also been shown to result in a reduction in tumor dispersion and invasiveness, as well as a reduction in secretion and activity of matrix metalloproteinase-2 (MMP-2)." (PMID 32532329, 2020). "Cannabinoids also curtail tumor invasion and metastasis by inhibiting the secretion of matrix metalloproteinase (MMP)-2 and MMP-9, while increasing the tissue inhibitors of MMP-1 (TIMP-1)." (PMID 33066359, 2020). "The anti-metastatic effect of compound 9 was associated with the inhibition of MMP-2 and MMP-9, two zinc-dependent endopeptidases associated with tumor invasion and metastasis, as well as the induction of angiogenesis." (PMID 32751120, 2020). "CH50, a recombinant polypeptide with bifunctional domains (CellI and HeparinII), was shown to inhibit tumor growth, metastasis, and regulate macrophages by down-regulation of CDC2, αvβ3 integrin, MMP-2/9 in the tumor microenvironment." (PMID 33329567, 2020). "The MPV-HOAD vesicles specifically accumulated in tumors and were activated by tumor acidity and MMP-2/9." (PMID 32317755, 2020). "MMP-2 regulates migration and invasion during tumor metastasis via extracellular matrix protein degradation." (PMID 32376896, 2020). "The crosstalk between cancer cells-derived fibronectin and stromal fibroblast plays a critical role for tumor metastasis via inducing MMP-2 upregulation." (PMID 33126605, 2020). "DKC1 knockout inhibits tumor proliferation, migration, and invasion by regulating the NF-κB/MMP-2 signaling pathway in vitro." (PMID 32528520, 2020). "The presence of MMP-2 in the stroma of the tumor is a protective factor while the presence of MMP-2 in the epithelium indicates an unfavorable prognosis." (PMID 32718331, 2020). "Upon silencing of EVA1A expression, the ability of flubendazole to induce autophagy and apoptosis was weakened in TNBC cells, while the tumor survival rate and MMP-2 levels were elevated." (PMID 32724459, 2020). "PGD2 can also decrease tumor MMP-2 expression, inhibit EMT inhibition, and reduce tumor cell proliferation." (PMID 32869161, 2020). "We demonstrated that inhibition of MMP2/9 by SB-3CT significantly reduced the tumor burden and improved survival time by promoting anti-tumor immunity." (PMID 32988398, 2020). "Neutrophils are the major contributors of MMP9 in the tumor microenvironment and contributors of MMP2 during chronic inflammation." (PMID 33049964, 2020). "After engraftment of MNNG/HOS cells in NOD/SCID/IL2rγnull mice, the stabilizing protein N-α-Acetyltransferase prevented degradation of MMP-2 and increased the ability of tumor cells to metastasize." (PMID 32377334, 2020). "Another study using murine brain slices found that microglia stimulated the extracellular matrix metalloprotease (MMP)-2, which led to increased invasiveness of the tumor." (PMID 32765498, 2020). "Several studies have reported CLIC1 to be an overexpressed protein in CRC, involved in cell migration and invasion, including more tumor recurrences and shorter patient survival, through the regulation of MMP-2 and MMP-9." (PMID 32353950, 2020). "Below, we summarized dynamic targeting strategies that use functional moieties sensitive to a variety of tumor microenvironment stimuli, including pH, matrix metalloproteinase‐2 (MMP‐2), and hyaluronidases." (PMID 32328428, 2020). "Overexpression of MMP-2 blocked the inhibitory effect of Porf-2 in tumor cell migration both in vitro and in vivo." (PMID 32676454, 2020).
tumor (continued). "In our study, abnormal hypermethylation of promoter CpG dinucleotides of the MMP2, MMP23B, MMP24, MMP25, and MMP28 was associated with HER2-positive tumor status, and, to a different extent, with CpG island hypermethylated epigenomic BC subtype." (PMID 32397602, 2020). "Gelatinases MMP-2 and MMP-9 have been implicated in many pathophysiological processes, such as tumor invasion and metastasis, but there are limited studies on the role of MMPs in mediating symptoms in patients undergoing adjuvant RT." (PMID 33134822, 2020). "Instead Timp1, the inhibitor of the matrix metalloproteinase 2 MMP2, was downregulated in U87AKDAPLNKO GBMs compared to the wildtype situation, and MMP2 itself, a proteinase degrading the extracellular matrix to support tumor cell invasion, was upregulated." (PMID 32545380, 2020). "Whereas, MMP2 expression can reverse the effect of Porf-2 in vivo, showing larger tumor volume and increased tumor weight." (PMID 32676454, 2020). "Different co-culture of CRC cell lines and TAM cell lines cause the upregulation of tumor cell-derived MMP-2 and MMP-9 expression and secretion, with increased tumor invasiveness and migration." (PMID 32984031, 2020). "It was demonstrated that after accumulation in the tumor bed with overexpressed MMP-2, these spherical nanoparticles underwent structural transformation into rod-like nanoparticles with prolonged drug retention time and deep tumor penetration capability." (PMID 32850662, 2020). "We used T cell cytotoxicity-mediated tumor killing assay to determine the co-cultured T cell activity of SB-3CT, an MMP2/9 inhibitor." (PMID 32988398, 2020). "ACPP-PpIX remained stable in blood circulation, while MMP-2 overexpressed on tumor cells can orient the targeted release of R9-PpIX for effective PDT." (PMID 34123123, 2020). "In the absence of MMP-2, the fluorescence of this system is quenched, while the presence of high levels of MMP-2 in the tumor restores fluorescence." (PMID 32042347, 2020). "Reports published in the literature indicated that MMP-2 can enhance the migration of HCC cells by increasing fibronectin cleavage and that the overexpression of MMP-9 is associated with HCC tumor migration and invasion." (PMID 32549236, 2020). "Metalloproteinases (MMPs) play a critical role in promoting tumor cell migration, extracellular matrix degradation and tumor distant metastasis, among them MMP2 and MMP9 are closely related to the proliferation, invasion and metastasis of ESCC." (PMID 32913452, 2020). "Studies found that dysregulated MMP2/9 in the solid tumors largely contributed to the tumor metastasis including HCC." (PMID 32117722, 2020). "CD147 can stimulate tumor cells to produce MMPs, specifically MMP-2 and MMP-9, especially in metastatic tumor cells." (PMID 33178600, 2020). "After ZLM-7 treatment, protein expression of Sp1, VEGFA and MMP-2 in tumor tissues decreased when compared to control group." (PMID 33187481, 2020). "Among the MMP family members, the gelatin-degrading enzymes MMP-2 and MMP-9 are associated with tumor ability to invade as their expression levels are often upregulated in the advanced stages of cancer." (PMID 32984054, 2020). "Strong cytoplasmic immunostaining of MMP-2 was observed mostly in the central cells of the islands formed by the tumour epithelium and in the peripheral cells of these islands." (PMID 33067558, 2020). "The results showed that GA reduced the level of MMP2 in the tumor cell lysate by 44.75% (GA, 40 mg/kg) or 48.46% (GA, 80 mg/kg), respectively, and in ascites fluid by 51.24% (GA, 40 mg/kg) or 53.70 (GA, 80 mg/kg) compared to the saline-treated control group." (PMID 33261130, 2020). "Recent publications and clinical trials have emphasized the potential value of measuring circulating or tissue MMP-2 levels as a tool for tumor diagnosis or prognosis prediction, or as a primary therapeutic target." (PMID 33115469, 2020).
tumor (continued). "IHC staining of intrahepatic tumor sections showed a decreased MMP‐2 and an increased E‐cadherin in HULC siRNA group." (PMID 34766115, 2020). "When injected into mice bearing orthotopic RCC xenografts, the RGD targeted the peptide monomers to the tumor where they were cleaved by MMP-2/9 and gradually self-assembled into nanofibers in situ." (PMID 32751865, 2020). "Taken together, our T cell tumor killing assay suggested that SB-3CT, an MMP2/9 inhibitor, can activate co-cultured T cell activity." (PMID 32988398, 2020). "Hyaluronic acid (HA) terminal groups were attached to PAMAM core through PLGLAG peptide linkages, which can be cleaved by MMP-2 at tumor sites, and the dendrimer will shrink from ~200 to ~10 nm." (PMID 33007959, 2020). "After treatment, the serum tumor marker levels along with serum MMP-2, MMP-9 and CD8+ levels in the test group decreased more remarkably, while CD4+ and CD4+/CD8+ levels increased more significantly than those in the control group (P < 0.05)." (PMID 33176740, 2020). "MMP-2/9 is not only involved in a variety of pathophysiological processes, but also play a promoting role in tumor invasion and angiogenesis." (PMID 32184893, 2020). "For instance, lowered tumor extracellular pH (pHe) and upregulation of the membrane protein matrix metalloproteinase 2 (MMP2) in the tumor microenvironment has been exploited as a strategy to improve the selectivity of plasmid DNA release." (PMID 33330106, 2020). "When PTX-ST-psMs accumulate at the tumor site, the MMP-2-sensitive peptide is degraded, and ST is released." (PMID 33261219, 2020). "The system retained good stability in blood circulation, and underwent degradation upon the action of MMP2, leading to enhanced uptake in tumor cells." (PMID 32887466, 2020). "Release of the gelatinases MMP-2 and -9 by tumor cells degrades matrices and/or basement membrane, which is a key step in invasion/metastasis." (PMID 33110606, 2020). "The EAPVs showed higher accumulation and retention in the tumors of a CT26 xenograft tumor model than they did in an MMP-2/9-insensitive control group, and the EAPVs showed increased ROS generation upon laser irradiation." (PMID 32317755, 2020). "Under hypoxia, the crosstalk between the HIF-1α, MMP-2, VEGF, and VEGFR-2 proteins has been associated with hypoxia-induced angiogenesis, leading to tumour progression and increased invasiveness." (PMID 33067558, 2020). "Through our computational analysis and in vitro assays, we revealed a potential mechanism in that MMP2/9 modulates the expression of PD-L1 in tumor cells." (PMID 32988398, 2020). "Upon accumulation in the tumor microenvironment, MMP-2 detached the sensitive linker, exposing the previously hidden CPP sequences on the surface of the assemblies and enhancing their cell-penetrating process." (PMID 34123123, 2020). "The prodrug vesicles also displayed improved tumor accumulation and penetration due to the acid‐activated charge reversal and MMP‐2‐sensitive de‐PEGylation." (PMID 33304763, 2020). "Our findings indicate that Porf-2 inhibited tumor cell migration through the MMP-2/9 signaling pathways via its GAP domain." (PMID 32676454, 2020). "The expression of GLUT1, MMP2, and cyclin D1 in the tumor tissues was also evaluated with western blot assays, and the results obtained were similar to the results in vitro." (PMID 32054829, 2020). "MMP-2 and MMP-9, both gelatinases, have been associated with tumor progression and tumoral angiogenesis, but in our analyses, MMP-9 had a different pattern of association." (PMID 32669083, 2020). "MMPs play an important role in tumor invasion and metastasis, and among many MMPs, MMP2 and MMP9 are well characterized in invasiveness and metastasis." (PMID 32029709, 2020). "In cancer pathology, MMP-2 and MMP-9 are mainly implicated in the formation of new blood vessels through angiogenesis; MMP-2 and MMP-9 facilitate the migration of tumor cells to blood vessels by the degradation of basement membrane ECM proteins." (PMID 32522053, 2020).
tumor (continued). "This MT1-MMP/MMP-2 cascade is highly effective in promoting tumour invasion through ECM degradation; however, there are some disadvantages to both types of MMPs." (PMID 32458057, 2020). "When octapeptide (GPLGIAGQ) was cleaved by MMP2, TATp was exposed, giving rise to the increased uptake of liposome particles by tumor cells." (PMID 32887466, 2020). "The expression of matrix metalloproteinase 2 (MMP2), which facilitates tumor invasion, has been shown to be significantly increased in HER2 subtype patients but not in TNBC patients." (PMID 32226776, 2020). "The two MMP-2 and MMP-9 have been associated with the malignant phenotype of tumor cells because of their unique ability to degrade type IV collagen, which is a major component of the basement membrane." (PMID 32353975, 2020). "MMP-2 (Gelatinase A) together with MMP-9 (Gelatinase-B) are related to tumor invasion and metastasis by their special capacity to degrade type IV collagen in basement membrane, and to induce angiogenesis." (PMID 33114046, 2020). "Thereby, inactivation of ERK1/2 would downregulate MMP-2/9 at the surface of cell resulting in the inhibited development and invasion of tumor cells." (PMID 32670867, 2020). "While it is established that increased VEGF and MMP2 expression can stimulate blood vessel growth and metastases and, thereby, contribute to tumor progression, TGF-β1 can have both, tumor-suppressing or pro-oncogenic effects." (PMID 32560387, 2020). "The inhibition of miR-21 causes the suppression of tumor cell invasiveness via the HIF-1/VEGF pathway and the downregulating of MMP-2 and MMP-9." (PMID 33321819, 2020). "Our results are consistent with prior findings that ACPPs can be cleaved by secreted MMP-2/-9 and the released CPPs are incorporated into cells displaying the gelatinase activity, for example, tumor cells and ischemic zones." (PMID 32372941, 2020). "A cell-penetrating peptide (R9GPLGLAGE8, ACPP) is sensitive to MMP-2 that is overexpressed in the tumor microenvironment." (PMID 34123123, 2020). "There is substantial evidence that MMP2 plays a major role in tumor cell-mediated degradation of extracellular matrix and its expression is closely related to the invasion, metastasis and prognosis of human malignant tumors." (PMID 33115469, 2020). "Matrix metalloproteinases (MMPs), especially MMP-2 and -9, are known to participate in various phases of tumor progression, including cancer cell invasion and tumor metastasis." (PMID 33374849, 2020). "As MMP-2 is overexpressed in inflammatory sites as well as in the tumor microenvironment, PC-Gla is released upon reaching MMP-2 activating sites." (PMID 32928251, 2020). "The gelatinases MMP-2 (gelatinase A) and MMP-9 (gelatinase B) are two members of the MMP family that are known to be associated with tumor invasion, metastasis and progression." (PMID 32024881, 2020). "Our results show a strong cytoplasmic immunostaining of MMP-2 in the central cells of the islands formed by the AME tumour epithelium, a region most likely to suffer intratumoral hypoxia." (PMID 33067558, 2020). "The combined analysis of MMP-2 and TIMP-2 with classical tumor markers (CA 19-9 and CEA) increased diagnostic sensitivity, however the highest value of this parameter was found for combined measurement of MMP-2 and TIMP-2 (96%)." (PMID 30719232, 2019). "MMP-2 is the most important metalloproteinase, is involved in tumor migration, invasion, and metastasis, and is also known to regulate inflammation." (PMID 31929819, 2019). "Gelatinases (MMP-2 and MMP-9) have been implicated in the induction of the angiogenic switch in different tumor models." (PMID 30792527, 2019). "In malignant melanoma cell lines with high reactive oxygen species (ROS), TAMs increased gene expression of mmp2, mmp9, mmp12, and ctsl proteases known to contribute to tumor invasiveness." (PMID 31737559, 2019).
tumor (continued). "Previous studies identified that miR-29c inhibited tumor invasion and metastasis by regulating different target genes and signaling pathways, such as MMP2 and the MAPK pathway." (PMID 31615536, 2019). "Increased ERK or PI3K/AKT activity results in enhanced MMP‐2 gelatinolytic activity involved in migration, invasion and tumour progression." (PMID 30838710, 2019). "A three-molecule complex consists of IBSP with αvβ3 and matrix metalloproteinase 2 (MMP2), which can enhance local matrix degradation and tumor cell invasion." (PMID 31709184, 2019). "The degradation and destruction of extracellular matrix (ECM) and basement membrane (BM) of tumor cell surface play important roles in tumor metastasis, to which MMP-2 and MMP-9 are recognized as the critical contributors." (PMID 30789971, 2019). "Western blotting and zymography analyses demonstrated that EtOH increases both the levels and the activity of MMP-2 and 9—two enzymes involved in tumor progression—and upregulates VEGF, the main angiogenetic factor." (PMID 30974805, 2019). "In fact, analysis of transcriptomic data indicated that PRLR expression is positively correlated with the levels of MMP-2 expression in tumour samples from GBM patients." (PMID 31862900, 2019). "MMP-2 in cancer tissues is able to induce tumor invasion and metastasis through the degradation of various protein components in the ECM." (PMID 31839752, 2019). "This ability was further confirmed by the strong positive correlation between tumour angiogenesis, as demonstrated by VEGF levels, and ECM production and tumour cell invasion tendency, as demonstrated by the MMP-2:TIMP-1 ratio." (PMID 31836811, 2019). "Mei’s work used an ACPP with PLGGLAG sequence which is the subtract of metalloproteinase 2 (MMP2) that is over expressed in tumour cells." (PMID 30634689, 2019). "When entering the acid niche in tumor cells, the protonated DEAP molecule caused unconsolidation of nanoparticle, and high level of MMP‐2 triggered the rapture of substrate peptide, leading to complete disruption of nanoparticle and instant drug release." (PMID 31508270, 2019). "Subsequently, the protein expression of MMP-2/-9 in the tumor xenograft tissues was detected by western blot analysis." (PMID 31632484, 2019). "For example, α3β1 integrin activates MMP-9 synthesis through interaction with laminins and triggers reorganization of the actin cytoskeleton; α6β1 is involved in tumor invasion via activation of the urokinase plasminogen activator (uPA) receptor and MMP-2." (PMID 31344926, 2019). "The PI3K/Akt/mammalian target of rapamycin (mTOR) and ERK pathways control the translation of HIF-1α, and HIF-1α activates VEGFs, u-PA, and MMP-2 and -9 to promote tumor metastasis." (PMID 31041568, 2019). "Members of the matrix metalloproteinase (MMP) family (such as MMP-2) are required for tumor invasion and metastasis." (PMID 30609689, 2019). "The ERK signaling pathway promoted tumor cell invasion and cancer metastasis through activation of MMPs, including MMP2 especially, contributing to the degradation of extracellular matrix." (PMID 30692511, 2019). "MMP-2 plays a significant role in angiogenesis and tumor formation, while MMP-9 is vital for metastasis and tumor development." (PMID 30708951, 2019). "Zymography analysis showed that HSCs cultures contained a higher expression of uPA and MMP-2 when exposed to tumor supernatants, and supernatants from C26 cells activated with sICAM-1 further promoted HSCs expression of these proteases." (PMID 31511625, 2019). "Matrix metalloproteinases-2 (MMP-2) are one of the overexpressed proteins in some tumors, which are closely related to tumor invasion and metastasis." (PMID 30986952, 2019). "High expression of matrix metalloproteinase-2 (MMP-2) was found to be correlated with tumor progression and poor prognosis in a variety of carcinomas." (PMID 31795085, 2019).